ALPK1 (alpha kinase 1)
Diseases named in the same sentence as ALPK1 in open-access papers (continued):
Sharing a sentence is not in itself a finding about the gene and the disease.
tumor (19 papers, 2016 to 2025). "nucleatum in tumor tissues of CRC patients was positively associated with the expression levels of ALPK1 and ICAM1." (PMID 35220887, 2022). "Here, the authors genetically assess a cohort of these adnexal tumours, highlighting recurrent ALPK1 mutations and revealing the genomic landscape of these rare tumours." (PMID 31101826, 2019). "Interestingly, in several cases (n = 5), we observed the ALPK1 p.V1092A mutation in the adjacent morphologically normal tissue (in addition to the tumor), from which the normal/germline DNA for somatic variant calling was extracted." (PMID 31101826, 2019). "This essential next step should be taken to directly link the ADP-heptose-ALPK1-TIFA axis to both a proinflammatory tumor microenvironment and an upregulated PD-L1." (PMID 39881579, 2025). "The consequence of ADP-heptose-mediated ALPK1 activation in these cells is a general pro-inflammatory response (which can be tumor-promoting), the downregulation of DNA mismatch repair genes and the upregulation of the checkpoint inhibitor protein PD-L1." (PMID 39881579, 2025). "Fusobacterium nucleatum releases ADP-H into the tumor microenvironment, triggering the ALPK1 (alpha kinase 1) signaling pathway, which activates TIFA (TRAF-interacting protein with FHA domain) and induces strong NF-κB activation." (PMID 39941737, 2025). "The findings from the CCK8 assay demonstrated that the reduction of ALPK1 notably decreased the growth of tumor cells (p < 0.01)." (PMID 39845963, 2024). "For instance, F. nucleatum has been shown to enhance the adhesion of CRC cells to endothelia cells, and in this way, promotes tumour progression and metastasis through upregulation of ALPK1 and ICAM1 expression." (PMID 36944721, 2023). "ALPK1 (alpha-kinase 1) inhibits spontaneous breast mammary bi-lineage tumor-initiating cell differentiation and is a potential target for therapeutic development." (PMID 35663314, 2022). "We found a strong re-expression of ERN1 and ALPK1 in the tumor cells arising from an ERN1 knockdown after late tumor passage." (PMID 27829216, 2016). "We present evidence for a role of ERN1 (endoplasmic reticulum to nucleus signaling 1), also known as IRE1 alpha (inositol-requiring 1), and ALPK1 (alpha-kinase 1) in inhibiting the spontaneous differentiation of mammary bi-lineage tumor-initiating cells." (PMID 27829216, 2016). "ALPK1 also displayed significant positive correlations with various immune suppressive molecules, potentially indicating its pivotal role in regulating specific stages of the anti-tumor immune cycle." (PMID 39845963, 2024). "The latest research has identified ALPK1 as a pattern recognition receptor that recognizes Fusobacterium nucleatum and upregulates the expression of ICAM1 through the ALPK1/NF-κB signaling pathway, thus promoting the adhesion, extravasation, and metastasis of tumor cells." (PMID 38169837, 2023). "The lower expression of ALPK1 in the tumor tissue samples of cancer patients implied that the disturbance of cell space polarization due to the reduction of ALPK1 expression might contribute to the initiation of tumorigenesis." (PMID 27283888, 2016). "Thus, we explored whether ALPK1 leads to tumor progression in Lovo and A549 cancer cells." (PMID 27283888, 2016).
infection (18 papers, 2017 to 2024). The state of being infected such as from the introduction of a foreign agent such as serum, vaccine, antigenic substance or organism. "Analysis of ALPK1 activity during S. flexneri infection showed that this PRR is activated within minutes of infection and that activation is maintained for several hours, most likely reflecting sustained ADPH release from intracellular bacteria." (PMID 37072480, 2023). "It has recently been demonstrated that heptose metabolites of LPS inner core biosynthesis can be considered novel PAMPs of Gram-negative bacteria as they activate human epithelial cells at early times of infection via the ALPK1-TIFA axis." (PMID 35408892, 2022). "Our results show that infection of intestinal epithelial cells with C. jejuni yields clear ALPK1-dependent inflammatory responses." (PMID 34339468, 2021). "Recent studies have indicated that the expression of ALPK1 during infection/inflammation can result in the activation of nuclear factor-kappa-B (NF-κB) signaling." (PMID 31101826, 2019). "Beyond its role during infection, ALPK1 is also involved in the control of intestinal homeostasis." (PMID 37072480, 2023). "Therefore, further studies on the mechanisms and role of ADP-heptose recognition by the ALPK1/TIFA pathway during infections with other pathogens are pending." (PMID 37317291, 2023). "The levels of inflammatory cytokines associated with the ALPK1/TIFA/NF-κB axis increased after infection with K. pneumoniae, but this was also independent of GmhB." (PMID 37317291, 2023). "Activation of the NF-κB transcription factor by ADP-heptose through the ALPK1/TIFA pathway induces the expression of inflammatory genes during infections with pathogens such as S. flexneri, S. typhimurium, N. meningitidis, Y. pseudotuberculosis, H. pylori, and C. jejuni." (PMID 37317291, 2023). "In order to test whether ALPK1 is phosphorylated during bacterial infection, HeLa cells were infected with the enteroinvasive bacterium S. flexneri at different multiplicities of infection (MOIs) and the thiophosphorylation status of GST-TIFA and myc-ALPK1 was analysed." (PMID 37072480, 2023). "Instead, Campylobacter releases ADP-heptose into its surroundings, both during culturing and during experimental infection of intestinal cells, from which ADP-heptose enters the host cells and activates ALPK1." (PMID 34339468, 2021). "In contrast, specific mutations in ALPK1 allow it to also be activated by endogenous human nucleotide sugars such as UDP-mannose, leading to the phosphorylation of TIFA in the absence of infection." (PMID 39600973, 2024). "The ALPK1/TIFA/NF-κB axis was also strongly activated during the infection of intestinal cells with C. jejuni, which do not possess such infective systems as T3SS or type IV secretion systems (T4SS) do." (PMID 37317291, 2023). "Only recently, a new function of ALPK1 as a PRR in innate immunity during infection with Gram-negative bacteria was discovered and reviewed." (PMID 37317291, 2023). "ALPK1 was then identified as a PRR in infections by Gram-negative bacteria, since its catalytic activity is essential for the self-oligomerization of TIFA." (PMID 35408892, 2022). "Here we demonstrate that the host proteins ALPK1, TIFA and TRAF6 act sequentially to activate the transcription factor NF-κB and regulate the production of chemokines in response to infection by the pathogens Shigella flexneri, Salmonella typhimurium and Neisseria meningitidis." (PMID 28222186, 2017). "In addition, we identify alpha-kinase 1 (ALPK1) as the critical kinase responsible for TIFA oligomerization and IL-8 expression in response to infection with S. flexneri and S. typhimurium but also to Neisseria meningitidis." (PMID 28222186, 2017). "In addition, infection with whole Gram-negative bacteria revealed a significant increase in all analysed TJ proteins in Alpk1−/− organoids, while RNA expression levels of Tjp1 and Cldn8 were decreased." (PMID 32076438, 2020).
infection (continued). "This revealed that infection with WT and ΔescN similarly activated ALPK1, determined by quantification of “TIFAsomes,” whereas no activation was seen by the ΔhldE, and as expected (due to accumulation of LPS metabolites), overactivation was seen by the ΔrfaC mutant." (PMID 31610608, 2020). "As with TIFA, depletion of ALPK1 failed to inhibit IL-8 expression and NF-κB activation observed after L. monocytogenes infection, suggesting a specific implication in infection by invasive gram-negative bacteria." (PMID 28222186, 2017). "AGS cells lacking ALPK1 or TIFA expression were resistant to replication fork slowing in this assay, both in the setting of live infection and of exposure to β-ADP-heptose." (PMID 33037203, 2020). "Altogether, these results show that HBP is a key bacterial PAMP sensed by epithelial cells during infection by both invasive and extracellular gram-negative bacteria and that TIFA/TRAF6-dependent innate immunity against HBP is controlled by ALPK1." (PMID 28222186, 2017).
cancer (13 papers, 2016 to 2025). A tumor composed of atypical neoplastic, often pleomorphic cells that invade other tissues. "Considering the role of Fusobacterium in cancer development, we next examined which cancer-related genes MSigDB Hallmark pathways were differentially regulated as result of ALPK1 activation." (PMID 39881579, 2025). "Mutations in ALPK1 have been recently described as associated or responsible for diseases, including inflammatory disorders and cancers." (PMID 37072480, 2023). "Because ALPK1 is associated with cancer development, the primary regulatory mechanism is activation of the NF-κB pathway through the inflammatory cytokine TNF-α." (PMID 36139553, 2022). "Of the four paired case–control studies included herein, three studies revealed that ALPK1 is strongly associated with cancer progression and metastasis, whereas one study demonstrated that ALPK1 is a driver of low- and high-grade spiradenocarcinoma." (PMID 36139553, 2022). "Indeed, ALPK1 was identified as the main intestinal inflammation regulator of the Helicobacter hepaticus-induced colitis and associated cancer susceptibility locus in mice." (PMID 37072480, 2023). "The literature concerning ALPK1 has been limited to examining the association of ALPK1 with cancer." (PMID 36139553, 2022). "Additionally, the levels of ALPK1 expression were associated with the infiltration of immune cells in various cancer types, where groups with high expression typically displayed increased concentrations of effector molecules related to immune cells in comparison to those with low expression." (PMID 39845963, 2024). "Furthermore, mutations in ALPK1 are associated with inflammatory syndromes and cancers." (PMID 37072480, 2023). "Lastly, we conducted a pan-cancer analysis, revealing significant correlations between ALPK1 and various immune checkpoints, including PD-L1, CTLA-4, LAG-3, and PDCD1." (PMID 39845963, 2024). "Researchers have used various forms of biotechnology and human, animal, and cellular models to better understand the relationship of ALPK1 with cancer and cancer-related inflammatory diseases." (PMID 36139553, 2022). "Studies involving human, animal, cellular, and tissue models support the relationship between ALPK1 and cancer and also suggest pathways and mechanisms of carcinogenesis." (PMID 36139553, 2022). "TNF-α production in dysplastic, primary, and metastatic ALPK1-depleted human oral (pre)cancer cells is reduced." (PMID 36139553, 2022). "Nonetheless, these studies also provide evidence supporting a relationship between ALPK1 and cancer." (PMID 36139553, 2022). "ALPK1 regulates downstream inflammatory mechanisms that lead to cancer development through certain pathways and plays a key role in cancer initiation and metastasis." (PMID 36139553, 2022). "High ALPK1 expression occurs in precancerous stages, such as oral cell dysplasia, and in skin lesions and persists in both early and advanced cancers, suggesting that ALPK1 is involved in many cancer stages from initiation to metastasis." (PMID 36139553, 2022). "The results showed that there were more fusiform cells and actin polymerization in ALPK1 overexpression A549 cancer cells compared to the other groups." (PMID 27283888, 2016). "Subcellular double staining with actin and DAPI was performed in ALPK1 knockdown and overexpression cancer cells, and then observed using confocal microscopy." (PMID 27283888, 2016). "We challenged multiple cancer cell lines with ERN1 or ALPK1 siRNA and assessed proliferation and colony forming ability from single cells." (PMID 27829216, 2016). "Likewise, the conserved bacterial metabolite ADP‐heptose activates ALPK1, differentially regulating cancer‐related pathways and significantly increasing PD‐L1 expression in an ALPK1‐dependent manner." (PMID 41216129, 2025). "Finally, the immune relevance of the model gene ALPK1 in the context of pan-cancer was explored, including its relationship with immune checkpoints." (PMID 39845963, 2024).
cancer (continued). "In the present systematic review, we search for and analyze the latest evidence regarding the role and mechanism of ALPK1 in the link between cancer and cancer-related inflammatory diseases and suggest the use of protein kinase inhibitors for the treatment of patients with cancer." (PMID 36139553, 2022). "However, the literature indicates that ALPK1 inhibitors and monoclonal antibodies are potential kinase-targeted therapies and anti-inflammatory drugs for preventing cancer progression and recurrence." (PMID 36139553, 2022). "ALPK1, a protein kinase, has also been linked to these cancer-related inflammatory diseases, but its association with cancer was not reported until 2016." (PMID 36139553, 2022). "Understanding the mechanisms by which ALPK1 and proinflammatory cytokines enter the nucleus may lead to the development of drugs that prevent cancer progression and metastasis." (PMID 36139553, 2022). "Different risk factors or carcinogens may lead to different pathways or translocation of ALPK1 into nuclei, thus altering the regulation of cancer progression." (PMID 36139553, 2022). "Thus far, however, there have been few investigations devoted to exploring the correlation between ALPK1 and cancer development." (PMID 27283888, 2016). "Taken together, these findings suggested that ALPK1 might play a vital role in cancer development and that the newly explored SNPs are found in a Taiwanese cohort." (PMID 27283888, 2016). "Therefore, we speculate that ALPK1 is most likely an oncogene that phosphorylates substrates and upregulates inflammatory mechanisms, thus contributing to cancer development." (PMID 36139553, 2022). "Until 2016, no data supported the association of ALPK1 with cancer." (PMID 36139553, 2022). "Future research should focus on identifying inhibitors of serine/threonine and ALPK1 at their phosphorylation sites, which would block various signal transductions and potentially offer kinase-targeted therapeutic agents for patients with cancer and inflammatory diseases." (PMID 36139553, 2022). "The phosphorylation substrate of ALPK1 is mainly myosin IIA, which is dysregulated in cancer and upregulated in inflammatory diseases, possibly having different phosphorylation sites." (PMID 36139553, 2022). "The 3D colony formation assay which is widely used to assess cancer stem cell self-renewal in vitro was more sensitive to the suppression of ERN1 and ALPK1 than the 2D assay." (PMID 27829216, 2016). "Besides this, rare and potentially pathogenic variants were identified in the DNA repair gene POLN and other cancer-related genes such as PPARG, CTC1, DCC and ALPK1." (PMID 36077770, 2022). "Alpha-kinase 1 (ALPK1) belongs to a newly discovered family of serine/threonine protein kinases with no sequence homology to conventional protein kinases, and its function in cancer is poorly understood." (PMID 36139553, 2022). "In the Lovo cancer cells, even though the change of the cell shape was not obvious, the average of fluorescence intensity of actin in the ALPK1 overexpression group was more slightly increased than in the other groups." (PMID 27283888, 2016). "According to MTT colorimetric assays, the forced expression of ALPK1 caused no obvious change in the viability of the Lovo and A549 cancer cells after 24 and 48 hours, nor was their viability changed in the ALPK1 knockdown group." (PMID 27283888, 2016).
bacterial infection (9 papers, 2019 to 2025). "A defect in Alpk1 could therefore contribute to a disruption of barrier function upon bacterial infection and be a cause for exacerbation of colitogenic inflammation." (PMID 32076438, 2020). "For example, copper has been demonstrated to augment the activity of alpha-kinase 1 (ALPK1), a cytosolic pattern-recognition receptor integral to host defense mechanisms against bacterial infections." (PMID 40589743, 2025). "ALPK1 is an atypical protein kinase that is activated during bacterial infection by ADP-heptose and phosphorylates TIFA to activate a cell signaling pathway." (PMID 39600973, 2024). "Recently, alpha-kinase 1 (ALPK1) controlling TIFA/TRAF6-dependent innate immunity against bacterial infection is gradually reported." (PMID 32420802, 2020). "Upon bacterial infection of IECs, ALPK1 has been shown to signal through TRIF/TRAF6 to NF-κB, triggering secretion of proinflammatory cytokines like IL8 and TNFα." (PMID 32076438, 2020). "Altogether, these results showed that the mechanism of ADPH sensing that occurs during bacterial infection induces the phosphorylation of both TIFA and ALPK1." (PMID 37072480, 2023). "These mutations allow ALPK1 to be activated by endogenous mammalian nucleotide sugars, such as UDP-mannose and ADP-ribose, in addition to bacterial ADP-heptose, leading to pathological signaling in the absence of bacterial infection." (PMID 39600973, 2024).
neurological diseases (1 paper, 2023). "Furthermore, it was discovered that several targets, such as DLG2, ETV5, PGM3, and ALPK1, were key regulators of neurological diseases." (PMID 36644780, 2023).
ALPK1 also shares sentences with these, for which no sentence is quoted: Retinal dystrophy (9 papers); Headache (6); hyperuricemia (3); dyslipidemia (2); endometrial cancer (2); Headache) syndrome (2); Hypertension (2); retinal disorder (2); adenocarcinoma (1); autoimmune disorders (1); autoinflammatory syndrome (1); Blau syndrome (1); Blindness (1); cervical adenitis (1); colon cancer (1); colorectal adenoma (1); colorectal tumors (1); cylindromas (1); diffuse large B-cell lymphoma (1); genetic disease (1); hypertriglyceridemia (1); intestinal tumor (1); ischemic stroke (1); liver fibrosis (1); macular edema (1); malaria (1); metastasis (1); myocardial infarction (1); non-small cell lung carcinoma (1); pancreatic cancers (1).
A further 5 diseases each share a sentence with ALPK1 in 1 paper.